GBA1 (glucosylceramidase beta 1)
Diseases named in the same sentence as GBA1 in open-access papers (continued):
Sharing a sentence is not in itself a finding about the gene and the disease.
Parkinson disease (continued). "However, accurately detecting variants, especially recombinant alleles resulting from a crossover between GBA1 and its pseudogene, is challenging, impacting studies of both GD and GBA1-associated parkinsonism." (PMID 37986861, 2023). "Furthermore, in a separate clinical study focused on Parkinson’s disease, GBA1 mutations had an enormous effect on its phenotype; specifically, the development of dementia symptoms in patients." (PMID 37629187, 2023). "Variants in the lysosomal hydrolase glucocerebrosidase (GCase), encoded by GBA1, may be associated with up to 15% of cases of the neurodegenerative movement disorder Parkinson's disease (PD)." (PMID 37908374, 2023). "Mutations in the GBA1 gene are also associated with risk of Parkinson’s disease." (PMID 36835039, 2023). "Mutations in GBA1 are causal for the rare autosomal storage disorder Gaucher disease, and they are also among the most commonly known genetic risk factors for the development of Parkinson’s disease and related synucleinopathies." (PMID 36361826, 2022). "GBA1 mutations are also the most common genetic risk factor for Parkinson’s disease." (PMID 35782380, 2022). "The study confirms the observed low penetrance of parkinsonism among GBA1 mutation carriers." (PMID 36330429, 2022). "This is an autosomal recessive inherited disorder caused by homozygous mutations in the GCase encoding gene (GBA1) affecting multiple organs, and in some cases causing parkinsonism, whereas heterozygous GBA1 mutations are the commonest genetic risk factor for PD." (PMID 36369100, 2022). "In addition, mutations in GBA1 are the most common genetic risk factor for future development of Parkinson's disease (PD)." (PMID 36330429, 2022). "In addition, we examined reports of neuropathologic studies conducted on patients with GD who developed parkinsonism and compared the findings to heterozygous GBA1-mutation carriers with parkinsonism, which are more frequently examined." (PMID 35628652, 2022). "Full sequencing of the GBA1 gene in patients with Parkinson’s disease provides a wide screening of pathogenic variants, but less developed regions of the world, like Latin America, may have difficulties in performing full sequencing." (PMID 35941142, 2022). "This longitudinal olfactory assessment in subjects with GBA1 mutations over a 16-year period is the largest and longest to date, following both homozygotes and heterozygotes including a large number with a family history of parkinsonism." (PMID 36330429, 2022). "Moreover, in Parkinson’s disease, it is well known that GBA1 mutation, reducing its lysosomal activity, is a high risk factor to develop Parkinson’s disease." (PMID 36077253, 2022). "Ultimately, these defects resulted in disrupted mitochondrial distribution and function, but could be rescued by TBC1D15 in Parkinson’s patient GBA1-linked neurons." (PMID 33753743, 2021). "These defects resulted in disrupted mitochondrial distribution and function, and could be further rescued by TBC1D15 in Parkinson’s patient derived GBA1-linked neurons." (PMID 33753743, 2021). "Glucosylceramidase beta (GBA1) gene mutations, responsible for the AR lysosomal storage disorder Gaucher disease, are a prominent example of this principle, having been identified as an important genetic risk factor for Parkinson disease." (PMID 34149605, 2021). "Also, a higher incidence of Parkinsonism in patients with GD harboring GBA1 homozygous mutations has been reported." (PMID 34194386, 2021). "Moreover, mutations in the GBA1 gene have recently been identified as the highest known genetic risk factor for Parkinson's disease (PD), further intensifying therapeutic interest in the GBA1 gene and enzyme." (PMID 34570911, 2021). "Among the lysosomal genes involved, GBA1 has the largest impact on Parkinson’s disease risk." (PMID 34151863, 2021).
Parkinson disease (continued). "Identification of the pathological mechanisms underlying GBA1-associated Parkinsonism might improve our understanding of the pathophysiology and treatment of GD in aging." (PMID 33672048, 2021). "Besides causing GD, GBA1 mutations constitute the main genetic risk factor for developing Parkinson’s disease." (PMID 32380730, 2020). "Carriers of GBA1 mutations are also highly susceptible to developing Parkinson’s disease (PD)." (PMID 32708198, 2020). "Although several explanations of the connection between GBA1 gene mutations and Parkinson disease onset were stated, the mechanism remains unclear." (PMID 32660097, 2020). "The presence of GBA1 gene mutations increases risk for Parkinson's disease (PD), but the pathogenic mechanisms of GBA1 associated PD remain unknown." (PMID 31634558, 2020). "Some have been demonstrated to reduce α-synuclein levels in pre-clinical studies using cell-based or animal models of GBA1-associated Parkinson disease, and may also have utility for idiopathic Parkinson disease." (PMID 32509770, 2020). "Furthermore, epidemiology studies demonstrated that family members of GD patients carrying heterozygotic-mutated GBA1 gene have significantly higher incidence of parkinsonism." (PMID 33330511, 2020). "Additionally, mutations in GBA1 are the most common genetic risk factor for Parkinson’s disease (PD), with a 5–20 fold increased risk of developing PD in GD patients or carriers of GBA1 mutations." (PMID 33287247, 2020). "Importantly, NCS-1 expression is reduced in iPSC-derived dopaminergic neurons from familial Parkinson’s disease patients heterozygous for the N370S mutation in the GBA1 gene." (PMID 31704946, 2019). "Lower CBE doses over a sustained period of time more closely resemble GBA1 mutation carriers, with approximately 50% residual GCase activity, and creates a more Parkinson-like phenotype, with increased oligomeric α-synuclein levels, brain-wide neurodegeneration, and microglial activation." (PMID 31464647, 2019). "Finally, there is a strong possibility that epigenetics plays a role in susceptibility to Parkinson disease by modulating the GBA1 gene." (PMID 31464647, 2019). "However, being a carrier for a pathological mutation in GBA1 is one of the strongest genetic risk factors for Parkinson’s disease, PDD and Lewy Body dementia." (PMID 30738426, 2019). "While the association between GBA1 and Parkinson disease is well-established, genetic modifiers may hold the key to elucidating GBA1-associated Parkinson genotype-phenotype correlation and underlying mechanisms of Parkinson pathogenesis." (PMID 31464647, 2019). "GBA1 mutations are also the most frequent genetic risk factors for Parkinson's disease." (PMID 31519738, 2019). "However, one study noted that although the incidence of Parkinson disease is similar in homozygote and heterozygote carriers of GBA1 mutations, the age of onset for homozygotes are approximately 6–11 years earlier than in heterozygotes." (PMID 31464647, 2019). "GBA1 mutations are also the most frequent genetic risk factors for Parkinson's disease, and decreased GCase enzyme activity is linked to α-synuclein accumulation and Parkinson's disease pathogenesis." (PMID 31519738, 2019). "Therefore, unlike certain genes leading to familial, monogenic forms of Parkinson disease, GBA1 mutations should be considered only as a risk factor for parkinsonism." (PMID 31464647, 2019). "GBA1 mutations have recently deserved increased attention upon the demonstration that both homo- and heterozygous GBA1 mutations represent the most important genetic risk factor for the appearance of synucleinopathies like Parkinson’s disease (PD) and dementia with Lewy bodies (LBD)." (PMID 30002620, 2018). "Additionally, endo-lysosomal morphology was disrupted and total lysosomal Ca2+ levels were reduced in fibroblasts from in Parkinson's patients with a mutation in GBA1." (PMID 29746898, 2018).
Parkinson disease (continued). "Glucocerebrosidase (GBA1) mutations are the major genetic risk factor for Parkinson’s Disease (PD)." (PMID 29362387, 2018). "Using this mouse model, we assessed the impact of D409H GBA1 mutation on the major phenotypes of the A53T α-synuclein Tg mice with disease onset and further examined the cardinal features seen in the GBA1-associated Parkinsonism through biochemical and immunohistochemical analyses." (PMID 29703245, 2018). "Altogether, our results provide novel insights into mechanisms by which GBA1 mutations may enhance Parkinson’s disease risk." (PMID 28969384, 2017). "However, both seasoned GD researchers and those new to the field have been limited by a dearth of effective models for studying both GD and GBA1-associated Parkinson's disease." (PMID 28592657, 2017). "Mutations in glucocerebrosidase 1 (GBA1) are the commonest risk factor for Parkinson’s disease." (PMID 28969384, 2017). "Our finding may well be relevant to the penetrance of GBA1 mutations in causing Parkinson’s disease, as it is currently estimated that 10–30% of individuals with GBA1 mutations will develop Parkinson’s disease by the age of 80." (PMID 28969384, 2017). "In addition, heterozygous mutations in GBA1 are significant genetic risk factors in the progression of Parkinson’s disease (PD) and Dementia with Lewy bodies (DLB)." (PMID 26629917, 2015). "This suggested that mutations in the GBA1 gene (coding for the glucocerebrosidase), and resultant alterations in sphingolipid metabolism, may contribute to biochemical changes found in Parkinson disease." (PMID 24307179, 2014). "Impaired activity, function or altered processing of glucocerebrosidase causes GD but the relationship of individual mutant GBA1 alleles and their effects on the structure and activity of the cognate β-glucocerebrosidase to the development of parkinsonism has yet to be determined." (PMID 22658918, 2012). "Therefore, research on LRRK2 and GBA1 may be essential to understand the biology underlying neuronal degeneration in Parkinson's disease." (PMID 40397198, 2025). "In 2009, a multicenter international collaborative study conclusively established the connection between GBA1 mutations and Parkinson disease (PD) highlighting GBA1 variants as common genetic risk factors for the development of PD." (PMID 37886493, 2023). "Variants in GBA1 are also the most common known genetic risk factor for Parkinson disease (PD) The presence of a highly homologous GBA1 pseudogene, GBAP1, located approximately 16kb downstream from the gene, complicates variant detection and sequence analyses." (PMID 37986861, 2023). "The discovery of glucocerebrosidase (GBA1) mutations as the greatest numerical genetic risk factor for the development of Parkinson disease (PD) resulted in a paradigm shift within the research landscape." (PMID 35932311, 2022). "Heterozygous GBA1 variants account for the most significant genetic risk factor for Parkinson disease (PD), the second most common neurodegenerative disease following Alzheimer’s disease with a reported prevalence rate of 315 per 100,000 persons worldwide." (PMID 35932311, 2022). "In addition, mutations in GBA1 are associated with Parkinson’s Disease (PD)." (PMID 35897658, 2022). "Ultimately, large multicenter studies confirmed that heterozygous GBA1 mutations is a genetic risk factor for both Parkinson disease (PD) and dementia with Lewy bodies (DLB), increasing the disease risk 5–10-fold, depending on the specific mutation." (PMID 35628652, 2022). "Moreover, GBA1 mutations are one of the main risk factors for developing Parkinson's disease (PD)." (PMID 35992201, 2022). "Classically associated with Gaucher disease (GD), a rare AR lysosomal storage disorder (LSD), GBA1 mutations are now known to be a common genetic risk factor for Parkinson disease (PD)." (PMID 34149605, 2021).
Parkinson disease (continued). "Heterozygous mutations of the lysosomal enzyme glucocerebrosidase (GBA1) represent the major genetic risk for Parkinson’s disease (PD), while homozygous GBA1 mutations cause Gaucher disease, a lysosomal storage disorder, which may involve severe neurodegeneration." (PMID 31685979, 2020). "The number of first‐degree relatives (excluding children) with Parkinson's disease was higher in p.D140H + p.E326K carriers (5.6%, 21 of 376) compared with p.E326K carriers (2.9%, 29 of 1014); OR, 2.0; P = 0.022, suggestive of a dose effect for different GBA1 variants." (PMID 32618053, 2020). "Mutations in the lysosomal glucocerebrosidase gene (GBA1) are the most significant genetic risk factor for Parkinson disease (PD)." (PMID 31251436, 2019). "Additionally, it remains unclear whether known Gaucher modifiers like prosaposin (PSAP) or LIMP2 (SCARB2) also play a role in patients with GBA1-associated parkinsonism." (PMID 31464647, 2019). "Interestingly, mutations in GBA1 gene could induce neurodegeneration and correlated with increased risk of developing Parkinson’s disease (PD)." (PMID 31555645, 2019). "Furthermore, population studies have established that individuals with GBA1 mutations, both carriers and affected individuals, are at an increased risk of developing Parkinson’s disease, an age-related neurodegenerative disorder, as well as other Lewy body disorders." (PMID 28592657, 2017). "Mutations in GBA1 have now been established as an important risk factor for the development of synucleinopathies including Parkinson disease (PD), dementia with Lewy bodies (DLB), and multiple system atrophy (MSA)." (PMID 27482815, 2016). "Moreover, interest in GD and nGD has recently been boosted by the realization that heterozygous mutations in GBA1 are a major risk factor for Parkinson’s disease, leading to the suggestion that GD therapies might be of use for treating Parkinson’s disease." (PMID 25775479, 2015). "Indeed, heterozygotes for GBA1 mutations occur with greater frequency in patients afflicted with Parkinson's disease and there is a pathogenic relationship between GCase alterations, mitochondrial dysfunction, and Parkinson's disease." (PMID 24124461, 2013). "We analysed rare variants (minor allele frequency < 0.01) across 36 lysosomal genes (excluding GBA1) in 8,267 individuals with Parkinson's disease and 68,208 controls, including a subset of 793 early-onset Parkinson's disease (≤50 years) cases." (PMID 41757160, 2026). "Eight loci-PRKN, SNCA, GBA1, LRRK2, APOE, MTHFR, SYT11, and NR4A2-emerged as recurrently associated with Parkinson's disease." (PMID 41798285, 2026). "GBA1 mutant neurons from Parkinson’s disease (PD) patients have been shown to have significantly decreased TBC1D15 levels and stabilized MLCs, correlating with the loss of activity of the lysosomal GCase (encoded by GBA)." (PMID 40002312, 2025). "Biallelic GBA1 p.L444P variants can result in all three types of GD19, 20 as well as monoallelic p.L444P associated with Parkinson disease." (PMID 39822020, 2025). "Parkinson’s disease is characterized by loss of dopamine neurons that project to the dorsal striatum, and mutations in LRRK2 and GBA1 are the most common genetic causes of familial Parkinson’s disease." (PMID 40737317, 2025). "A clear understanding of the mechanism-of-action of these compounds will facilitate development of GBA1-modulating drugs for Parkinson's disease." (PMID 41459692, 2025). "Variants in the GBA1 gene are the commonest genetic risk factor for Parkinson disease (PD)." (PMID 41034226, 2025). "Decreased GCase activity in both GBA1-Parkinson’s patient neurons and GCase inhibitor-treated cells is associated with extended MLCs, elevated lysosomal pH, and mitochondrial dysfunction." (PMID 40002312, 2025). "It is currently understood that more than 20 genes areassociated with Parkinson’s disease, the most prevalentmutations of which are found in the GBA1, LRRK2, PRKN,and PINK1 genes." (PMID 40144372, 2025).
Parkinson disease (continued). "This study demonstrates that food-derived plasma metabolites are significantly altered in Parkinson’s disease and show subtype-specific associations with clinical severity, particularly in carriers of LRRK2 and GBA1 mutations." (PMID 41515898, 2025). "As expected however plasma gpNMB concentrations among patients with Parkinsonism were higher in those with type 1 Gaucher disease than either GBA1 heterozygotes or those with idiopathic PD (p=0.0001)." (PMID 41152894, 2025). "This supports the promotion of universal access to genetic testing for Parkinson’s disease, as well as therapeutic trials for GBA1 and LRRK2-related Parkinson’s disease." (PMID 39074992, 2024). "There are a number of genes that are found in both aspects of genetic risk for Parkinson's disease—SNCA but also LRRK2 on chromosome 12 and GBA1 on chromosome 1." (PMID 38368938, 2024). "Among them, CRKL, one of the significantly upregulated proteins in GBA1-PD CSF, positively correlated with the Unified Parkinson’s Disease Rating Scale part III (UPDRS-III) scores in iPD, which showed the opposite correlation in GBA1-PD." (PMID 38203854, 2024). "Two of these loci, APOE and BIN1, are known as risk loci for AD15, while three—SNCA, GBA1, and TMEM175—have been found in Parkinson’s disease (PD) GWAS16." (PMID 39572598, 2024). "An extensive screening of GBA1 variants was previously performed by our team using GBA1-targeted PacBio sequencing in individuals from the Luxembourg Parkinson’s study (660 PD patients, 100 patients with other forms of parkinsonism and 808 controls)." (PMID 38173558, 2023). "Clinical and genetic evidence clearly show that variants in ApoE and GBA1 are the highest risk factors for Lewy body dementia (LBD) and dementia onset in Parkinson’s disease (PD) patients." (PMID 37947642, 2023). "Investigations into the factors that lead to discordant phenotypes and aggravated DA release defects will be important not only to understand GBA1-related Parkinson’s disease, but also for understanding sporadic disease pathogenesis." (PMID 36864664, 2023). "Parkinson’s disease patients who carry both APOE4 and GBA1 variants have accelerated cognitive decline compared to single variant carriers." (PMID 37947642, 2023). "Mutations in GBA1, which encodes the lysosome enzyme β-glucocerebrosidase (also referred to as acid β-glucosidase or GCase), are the most common genetic risk factor for Parkinson disease (PD) and dementia with Lewy bodies (DLB)." (PMID 37886493, 2023). "A link between α-synuclein and GBA1 was suggested when intraneuronal α-synuclein inclusions were observed in GD type 1 patients with parkinsonism." (PMID 36768367, 2023). "Variants in the GBA1 and LRRK2 genes are the most common genetic risk factors associated with Parkinson disease (PD)." (PMID 36034282, 2022). "They obtained neurons from a Parkinson’s disease patient harboring mutant GBA1, a lysosomal enzyme catalyzing the hydrolysis of glucosylceramide, and the greatest genetic risk factor for PD." (PMID 35625553, 2022). "NCGC607 not only restored GBA1 activity, but also reduced α-synuclein levels in dopaminergic neurons generated from iPSCs derived from GD patients with Parkinsonism." (PMID 35725499, 2022). "The enzymatic activities of both GBA and LRRK2 are closely linked to their role in the etiology of Parkinson’s, with loss of glucocerebrosidase (GCase) activity due to mutations in GBA1 and a likely gain of kinase activity due to mutations in LRRK2." (PMID 35805938, 2022). "GD-iMphs had a decreased GBA1 activity and stored glucosylceramide and glucosylsphingosine; GD-neurons derived from patients with Parkinsonism had a reduced dopamine storage, a reduced dopamine transporter reuptake and elevated α-synuclein levels." (PMID 35725499, 2022). "Variants in GBA1 are a significant genetic risk factor for Define- Parkinson disease (PD)." (PMID 34234814, 2021).